YAP1 (Yes1 associated transcriptional regulator)
Diseases named in the same sentence as YAP1 in open-access papers (continued):
Sharing a sentence is not in itself a finding about the gene and the disease.
colon carcinoma (71 papers, 2014 to 2026). "Rosenbluh reported that in the development of colon cancer, the compounds formed by β-catenin, yes-associated protein 1 (YAP1) and TBX5 were essential for survival of colon cancer, similar phenomena were observed in other tumors." (PMID 38413457, 2024). "In a study, HMGB1-mediated RAGE activation was shown to reduce the accumulation of transcription factor Yes-associated protein-1 (Yap-1) in colon tumor cells in a RAS-dependent manner." (PMID 35296101, 2022). "Here, we demonstrate that YAP1 expression is associated with M2 tumor-associated macrophage polarization and the generation of colon cancer stem-like cells." (PMID 28241877, 2017). "An increased YAP1 expression was found to be associated with a poor prognosis in patients with colon cancer using bioinformatics approach." (PMID 28241877, 2017). "An association between worse prognosis and YAP1 overexpression has been previously reported in colon cancer, ovarian tumors and medulloblastoma." (PMID 27705928, 2016). "Furthermore, a recent clinical study demonstrated that YAP1 activation was associated with the poor prognosis and certuximab resistance in colon cancer patients." (PMID 28241877, 2017). "Moreover, loss of YAP1 expression also contributed to inhibition of colon cancer cell (DLD1 and HCT116 cells) growth, clone formation, invasion, and migration." (PMID 28356122, 2017). "This is achieved through the interaction between USP2-AS1 and LATS1, which leads to the activation of YAP1, thereby promoting colon cancer cell proliferation, migration, and invasion." (PMID 39431199, 2024). "Second, YAP collaborates with other transcription regulators to alter gene expression, for example, in colon cancer cell lines YAP1, β-catenin, and TBX5 transcriptional complex regulate (TCF- or TEAD-independent) target genes." (PMID 38730720, 2024). "The modulation of the Hippo/YAP1 signaling pathway by the lncRNA USP2-AS1 is a crucial factor in the promotion of colon cancer progression." (PMID 39431199, 2024). "MYL9 interacts with the transcriptional regulator YAP1 in colon carcinoma cells and alters the expression of YAP1-regulated genes." (PMID 35802750, 2022). "IHC staining also identified that YAP1 was upregulated in colon cancer tissues versus normal colonic mucosa tissues." (PMID 36479120, 2022). "At last, we verified the contribution of Hippo/YAP1 signaling in the GABABR1 down-regulation impaired biological phenotype of colon cancer cells in vivo." (PMID 34131398, 2021). "Recently, a new network was discovered between IL-6 and YAP1, which led to an increase in colonic tumor formation." (PMID 33807620, 2021). "LncRNA B4GALT1-AS1 facilitates colon cancer cell stemness via recruiting YAP1 to the nucleus and enhancing YAP1 transcriptional activity." (PMID 33763375, 2021). "Here, we further show the ability of TONDU peptide to inhibit proliferation of prostate and colon cancer cell lines with elevated YAP1 levels." (PMID 32540914, 2020). "The YAP1-specific inhibitor peptide 17 dramatically attenuated colon cancer cell proliferation, migration, and invasion promoted by circPPP1R12A-73aa overexpression." (PMID 32019587, 2020). "From a transcriptional point of view, several studies employing colon cancer cells have depicted a regulation of YAP1 transcription by ß-catenin, HIF1α, p65 NFκB, TEAD4 or CREB." (PMID 33126419, 2020).
colon carcinoma (continued). "The importance of this mechanism is strongly supported by nuclear DUSP10 and nuclear YAP1 presence in tumor tissue of colon cancer patients; and more importantly, poor prognosis is related to high nuclear DUSP10 expression." (PMID 31717606, 2019). "We explored the public databases to show that YAP1 network is upregulated in clinical colon cancer samples and cell lines." (PMID 28241877, 2017). "Replication of these experiments in the SW620 colon cancer cells generated similar results, suggesting that YAP1 is an essential mediator of platelet-induced anoikis resistance in various types of cancer cells." (PMID 28827520, 2017). "YAP1 downregulation by gene silencing or a phytochemical, ovatodiolide, not only suppresses colon cancer tumorigenesis but also prevents M2 TAM polarization." (PMID 28241877, 2017). "We showed that exogenous IL-6 led to the increased generation of colon tumor spheres with concomitant elevated YAP1 expression, establishing a novel link between YAP1 and IL-6 network." (PMID 28241877, 2017). "YAP1 was proposed to functioning either partially or in tandem with key oncogenic drivers such as Kras, β-catenin, and Akt/mTOR in colon tumor initiation and progression." (PMID 28241877, 2017). "We showed an increased YAP1 expression in the colon spheres, and colon cancer cells co-cultured with M2 TAMs." (PMID 28241877, 2017). "The accordant increase of YAP1 and Ascl2 in human colon cancer samples was consistent with the observations in vitro." (PMID 29312609, 2017). "Taken together, we suggest that YAP1/KLF5-activated Ascl2 expression in colon cancer progenitor cells confers their self-renewability." (PMID 29312609, 2017). "In colon cancer, the reduction of YAP1 expression triggered hyperactivity of the Wnt/beta-catenin pathway, supporting the link between Hippo/YAP1 signaling and the Wnt/beta-catenin pathway." (PMID 27705928, 2016). "Of equal importance, the majority of patient samples on a colon cancer tissue microarray displayed an inverse correlation between high YAP1 and low NDR2 levels." (PMID 25601544, 2015). "Phosphorylation of YAP1 at S127 by NDR mediates sequestration of YAP1 in the cytoplasm, restricts the transcriptional coactivator function of YAP1, and suppresses proliferation of human colon cancer cells." (PMID 25601544, 2015). "Functionally and in full support of our finding that NDR negatively regulates YAP1 activity, NDR impairs proliferation and colony formation of YAP1-dependent colon cancer cells." (PMID 25601544, 2015). "Additionally, through immunohistochemical staining analysis of paraffin sections from COAD patients, we discovered that the expression levels of GLS and YAP1 proteins in colon cancer tissues were also significantly upregulated." (PMID 41152153, 2025). "Moreover, RT‐PCR and immunohistochemical analyzes confirmed that the expression levels of GLS and YAP1 were significantly upregulated in colon cancer tissues." (PMID 41152153, 2025). "A recent study demonstrated that brusatol could inhibit the malignant behaviors of colon cancer by upregulating ARRDC4 expression-a cancer glycolytic inhibitor- while modulating PI3K/YAP1/TAZ pathway." (PMID 38581008, 2024). "In colon cancer, upregulated expression of YAP1 was shown to promote EMT and tumor aggressiveness." (PMID 38444414, 2024). "YES1 and YAP1 interact within the context of β-catenin-active colon cancer SW480 cells." (PMID 38338729, 2024). "In the colon cancer cells treated with 100 μM of both OA and PA, a significant (p < 0.001) increase of YAP1 could be observed in the nuclear compartment." (PMID 37117602, 2023). "In addition, METTL3 increases the expression of PTTG3P through an m6A/IGF2BP2-dependent mechanism and regulates the PTTG3P/YAP1 axis to induce colon cancer cell proliferation and promote colon cancer progression." (PMID 35614935, 2022).
colon carcinoma (continued). "circPPP1R12A was found to have an oncogenic function 73, 106, whereas circ0106714 showed tumor suppressive function as its upregulation reverted the malignant phenotype of colon tumor cells through miR‐942‐5p sponging mechanisms that led to enhanced YAP1 phosphorylation." (PMID 35673576, 2022). "Finally, to demonstrate the specificity of the YAP1 shRNA effects, we evaluated the same doxycycline inducible YAP1 shRNA knockdown construct in a Hippo pathway independent colon cancer model, HCT116." (PMID 35689194, 2022). "Rescue experiments showed that circ1662 promotes EMT in colon cancer depending on YAP1 protein." (PMID 33754062, 2021). "Gene silencing or VP-mediated inhibition of YAP1 downregulated both factors in colon cancer cells." (PMID 33178014, 2020). "YAP1 is expressed in several tissues but is especially highly expressed in colon cancers." (PMID 31216773, 2019). "Moreover, VP has been suggested as a specific inhibitor of the YAP-1 protein whose role is important in the biology of colon carcinoma." (PMID 30263014, 2018). "When 100 pmol of control miRNA, miR-15a or Mimic-1 was added to colon cancer cells growing in 2 ml regular growth medium (50 nM), we found that protein expression of target genes YAP1, and BMI1 was reduced in cells three days after treatment with Mimic-1, but not in cells treated with miR-15a." (PMID 29416778, 2018). "In colon cancer patients, YAP1 expression correlates with poor prognosis and chemoresistance." (PMID 29416778, 2018). "In colon cancer, YAP1 promotes invasion, migration, cell growth and EMT." (PMID 29416778, 2018). "Moreover, upregulation of miR-195-5p suppresses proliferation, migration, invasion, and EMT of colon cancer cells through targeting the YAP1 mRNA 3′-UTR." (PMID 28356122, 2017). "Collectively, these findings support our hypothesis that YAP1 represents a key target for therapeutic development in colon cancer patients." (PMID 28241877, 2017). "However, verteporfin can act as an autophagosome inhibitor by promoting oligomerization of p62 and inhibit colon cancer progression independently of YAP1." (PMID 27911857, 2017). "One possibility is that in metastases, TEAD/YAP1 signaling interacts with HH-GLI instead of WNT-TCF: HH-GLI signaling drives colon cancer metastases, and its interaction with TEAD/YAP1 could parallel the interaction described in medulloblastoma." (PMID 24920608, 2014). "Moreover, YAP-1 overexpression in our study may suppress autophagy in colon cancer cells through elevated BCL-2 levels since YAP and TEAD cooperation promotes BCL-2 production, potentially enhancing cell survival by deterring autophagy-related cell death." (PMID 38755413, 2024). "To further determine whether YAP1 could ensure the self-renewability of colon cancer progenitor cells, we established YAP1-enforced HT-29 (lv-YAP1/HT-29) and Caco-2 (lv-YAP1/Caco-2) cell lines with lentivirus particles using an LV5 (EF-1aF/GFP & Puro) vector with a YAP1 insert." (PMID 29312609, 2017). "Thus, YAP1 could represent an important druggable target; ovatodiolide could be further evaluated and considered to be used as an adjuvant agent for treating colon cancer." (PMID 28241877, 2017). "While both YES1 and Src can phosphorylate YAP1 at the Tyr-357 residue, only YES1 is crucial for the survival of β-catenin-active colon cancer cells." (PMID 38338729, 2024). "In mammary epithelial cells and colon cancer HCT116 cells, YAP1/TAZ can enhance autophagy by promoting Armus activities." (PMID 37665055, 2023). "We also observed that strong positive correlations for CARD10-YAP1, YAP1-RELA, and YAP1-SNAI2 in patients with colon cancer." (PMID 34885061, 2021).
colon carcinoma (continued). "Analysis using the GEPIA dataset indicates that the YAP1 levels were positively correlated with TEAD1 in colon cancer, rectal cancer and CRC, and surprisingly, the YAP1 and TEAD1 levels were both positively correlated with HIF1A or LDHA." (PMID 33218358, 2020). "With these important targets of miR-15a, (BCL2, BMI1, YAP1 and DCLK1) in colon cancer having potential to promote colon cancer growth, we investigated the effects of miR-15a on cell proliferation." (PMID 29416778, 2018). "YAP1 regulates the expression of SOX2 and c-MYC, which are overexpressed in colon cancer and promote metastasis and tumor growth." (PMID 29416778, 2018). "Several important colon cancer related genes, including well established targets of miR-15a, BCL2 and BMI1 as well as novel targets, YAP1 and DCLK1 contain binding sites for miR-15a in their 3’UTRs." (PMID 29416778, 2018). "A correlation between YAP1 and Ascl2 was present not only in the CD133+CD44+ CRC cell population but also in colon cancer tissue samples." (PMID 29312609, 2017). "In support, using a colon tissue microarray, we identified a strong YAP1 expression in the late stages (stages IIIB, IIIC, IVA, and IVB) colon cancer samples." (PMID 28241877, 2017). "Analysis of human colon cancer samples further revealed that NDR2 and YAP1 protein expression are inversely correlated in the majority of samples with high YAP1 expression." (PMID 25601544, 2015). "To increase the spectrum of our analysis, we assessed YAP1 and NDR2 protein levels in a tissue microarray with 325 independent human colon cancer samples." (PMID 25601544, 2015). "Beyond the Hippo pathway, the prostaglandin E (PGE) signaling pathway enhances YAP1 expression and activity, upregulating cyclocyception 2 and prostaglandin E receptor 4 (EP4), stimulating colon cancer cell proliferation and colon tissue regeneration in colitis mice." (PMID 40066231, 2025). "Dual-targeting Yap1 and Cox2 solely in Panc02 cells or in fibroblasts had no discernable effect on Gem response, unlike previous reports that dual-targeting Yap1 and Cox2 only in cancer cells enhances chemotherapy efficacy in colon cancer and bladder cancer." (PMID 39468013, 2024). "Finally, high expression level of CYGB had the close correlation with key genes YAP1 and ACSL4 in ferroptosis pathway in colon cancer based on analysis from TCGA data." (PMID 33611811, 2021). "Furthermore, over-expressing miR-590-3p inhibited expressions of LATS1 and SAV1, promoted YAP1 expression and didn’t effect MST1 expression in colon cancer cells." (PMID 28938537, 2017). "To investigate whether NDR kinases function as YAP1 kinases in mammalian cells, we overexpressed NDR in the colon cancer cell line SW480 and assessed S127 phosphorylation." (PMID 25601544, 2015). "Considering that YAP1 drives proliferation in colon cancer and that NDR negatively regulates YAP1 levels and activity, we asked next whether NDR negatively affects YAP1-dependent proliferation of human colon cancer cells." (PMID 25601544, 2015). "Recent studies demonstrate that growth inhibition after VP treatment is independent of YAP1 expression or that of the related Hippo effector TAZ in colon cancer, which is in line with our finding that YAP1 expression did not correlate with sensitivity to VP in GC cell lines." (PMID 29228735, 2017). "Previous studies have confirmed that YAP1 may partially reverse the inhibitory effect of SNTB1 knockdown on the phenotype of CRC cells and the Wnt/β‐catenin/MYC signaling pathway, thereby affecting the invasiveness of colon cancer cells and the growth and metastasis of tumors in vivo." (PMID 41152153, 2025). "Importantly, we show that the THBS1/YAP1 signalling axis we discovered in organoids is conserved in both mouse and human colon cancer and propose that this early mechanism of non-cell-autonomous epithelial communication is critical for the establishment of a primary tumour." (PMID 35543624, 2022).
colon carcinoma (continued). "Another study confirmed the negative correlation between miR-550a-3-5p and YAP1 in colon cancer tissues, and showed that miR-550a-3-5p could repress tumor cell proliferation, metastasis, and sphere formation by directly inhibiting YAP1 and its oncogenic pathway in various cancer cell types." (PMID 34530822, 2021). "In colon cancer cell lines, which are not typically considered hormone sensitive, zearalenone promoted anchorage-independent cell growth and cell cycle progression, which was suppressed by G15, via MAPK and Hippo pathway effector YAP1, providing a mechanism for promoting colon cancer growth." (PMID 36662583, 2023).